IGF1R (insulin like growth factor 1 receptor)
Diseases named in the same sentence as IGF1R in open-access papers (continued):
Sharing a sentence is not in itself a finding about the gene and the disease.
cancer (continued). "Similarly, the membrane-associated insulin-like growth factor 1 receptor can be sumoylated at the three conserved lysine residues for its translocation to the nucleus to exert its roles in development and cancer biology." (PMID 35498700, 2022). "Elevation in IGF1R levels may contribute to the proliferative effects associated with initiation of prostate (and other) cancer." (PMID 36479090, 2022). "Moreover, IGF-1R signaling is also implicated in cancer development due to its stemness-related properties and resistance of radiation therapy and chemotherapy." (PMID 36233084, 2022). "Interestingly, high levels of IGF-1/ IGF1-R were also reported to be associated with poor OS and cancer aggressiveness in RCC." (PMID 33882870, 2021). "Notably, human cancers are frequently mutated in the IGF-1R (2.48% of all cancers) and in its downstream signaling proteins Ras (19% of all cancers) and Akt (1.8% of all cancers)." (PMID 34572814, 2021). "Furthermore, nuclear IGF-1R has been linked to a poor outcome for cancer patients and suggested to promote a more advanced disease stage." (PMID 33584548, 2020). "In particular, it has been reported that the nandrolone-induced proliferation of different cancer cell lines is linked to the activation of the insulin-like growth factor 1 receptor (IGFR1)-mediated signaling with the maximal effect attained at a concentration as low as 1 μM of the drug." (PMID 32041983, 2020). "Thus, high levels of IGF1R are associated with increased incidence of cancer progression, whereas lower levels of IGF1R are associated with decreased incidence of cancer progression in CRC cell lines." (PMID 30965609, 2019). "Besides, the increased IGF-1R activity is implicated in cancer cell function such as cell migration, proliferation, and invasion." (PMID 31217907, 2019). "Therefore, increased IGF1R signaling is linked with an elevated cancer risk and induces more aggressive behaviors of cancers." (PMID 30404198, 2018). "The IGF1R signaling pathway is implicated in the pathogenesis and progression of cancer." (PMID 30013477, 2018). "IGF‐1R signaling has been reported to promote cell proliferation, survival, and hypertrophy, and is strongly implicated in the development and progression of human cancer." (PMID 28112398, 2017). "Also the high serum concentration of IGF1R is associated with the risk of many cancers such as breast, prostate, colorectal, and lung cancers." (PMID 27405474, 2016). "Furthermore, IGF-1R expression and activation is associated with resistance to cancer therapy such as chemotherapy and radiotherapy." (PMID 27813495, 2016). "We investigated the mechanisms underlying the IGF-1R blockade-induced cancer metastasis." (PMID 26465273, 2015). "DDR1 is also over-expressed in many cancers and it associates with the IGF-1R." (PMID 26191041, 2015). "Targeting IGF-1R might lead to improved personalized therapeutic approaches in cancer patients with HR deficiency." (PMID 26510816, 2015). "However, little is known regarding the molecular mechanisms underlying IGF1R gene dysregulation in cancer." (PMID 25092925, 2014). "Encouragingly, recent endeavors have led to the identification of potential biomarkers that may be associated with the sensitivity of cancer cells to anti-IGF-1R antibodies, although a unified theme is still wanting." (PMID 22952934, 2012).
cancer (continued). "Deregulated IGF1R kinase activity has been linked to human cancer." (PMID 22778948, 2012). "Mutations in IGF-2R have been found in many types of cancer (see Discussion), and may predict response to IGF-1R inhibitors." (PMID 22022506, 2011). "The molecular mechanisms that regulate anoikis in invasive cancer cells are poorly understood, but we have demonstrated that loss of C/EBPβ expression renders cells more susceptible to anoikis, even in the presence of IGF-1R signaling." (PMID 21854628, 2011). "High level expression of IGF-1R has been implicated in several different cancers." (PMID 22072919, 2011). "In contrast, the synergy in growth reduction was observed to parallel a synergy in apoptosis induction (IC75 CI=0.62 at AG 1024 2.5 μM and AG 1296 5.0 μM), pointing to a cytotoxic effect in these cancer cells associated with the co-targeting of IGF-1R and c-kit." (PMID 15150607, 2004). "Given the observation that factor 1 was associated with IGF1R signaling and mTOR inhibitor treatment led to an increase in factor 1 scores, we hypothesized that mTOR inhibition leads to a reactive upregulation of IGF1R signaling in cancer organoids." (PMID 35668108, 2022). "Thus, researchers speculate that similar insulin analogs that show high affinity for IGF-1R in vitro may have pro-proliferative and cancer-causing effects." (PMID 31555212, 2019). "The increased expression of MEK and phosphorylated ERK and the concomitant decrease in IGF2 and IGF-1R expression in co-culture conditions might also indicate a shift from the endogenous paracrine IGF2 axis towards a cancer promoting ASC-associated leptin axis." (PMID 31817072, 2019). "Clinically ineffective IGF1R-directed therapies may be associated with the ability of the cancer cell to re-activate the signaling pathway in addition to alternative activation of downstream IGF1R signaling pathways by other growth-promoting receptors in the cell such as HER2/3, EGFR and InsR." (PMID 29207959, 2017). "Finally, a relevant question is whether genetic events might be linked to IGF1R overexpression in cancer." (PMID 27446805, 2016). "Importantly, this work provides a new paradigm for MK-2206-mediated control of aberrant cell survival associated with IGF1R-dependent CRC that may offer new targets for enhancing cell death in cancer cells." (PMID 24581231, 2014). "Recent studies have explored IGF1R involvement in integrin function and cancer cell adhesion dynamics." (PMID 42244949, 2026). "In other cancers, it has been reported that targeting IGF1R signaling can enhance the sensitivity of cisplatin in oesophageal squamous cell carcinoma (OSCC)." (PMID 39901877, 2025). "Herein, we expand upon our prior work demonstrating that oHSV-induced IGF2/IGF1R signaling promotes immunosuppression to explore its impact on cancer cell survival and resistance." (PMID 41510300, 2025). "Increased IGF1R expressions likely suppresses differentiation by promoting cellular proliferation, a mechanism commonly observed in cancer biology." (PMID 40279337, 2025). "The findings highlight the essential function of the IGF2/PI3K and the role of CAFs in ASCC growth, highlighting that IGF2/IGF1R inhibitors are potential treatment options for this cancer." (PMID 40740483, 2025). "Mechanistically, miR-99b-5p inhibits cancer progression by targeting insulin-like growth factor 1 receptor (IGF1R) and regulating EMT." (PMID 40556678, 2025). "The evaluation of IGF1R immunostaining encompassed the examination of membranous (m-IGF1R) and cytoplasmic (c-IGF1R) IGF1R expression in cancer cells." (PMID 39775131, 2025). "Overexpression of IGF-1R has been observed in various cancers, such as breast, lung, and prostate cancer, where it is associated with aggressive tumor behavior and resistance to therapy." (PMID 40071065, 2025).
cancer (continued). "Western blot analysis demonstrated that cancer serum induced 2.8-fold and 2.5-fold activation of IGF-1R and c-MET autophosphorylation, respectively, with corresponding downstream AKT phosphorylation." (PMID 40804939, 2025). "Notable downregulated genes included Mki67, Ccn1, Muc1, Atf3, Ntrk2, Arid5b, Igf1r, Igf2bp2, Cd47, and Cd37 (oncogenic function) and integrin-related genes, Itga7, Itga11, Itgam and Notch1 (cancer stem cell markers)." (PMID 39946195, 2025). "Single-cell studies identify COL11A1+ CAFs as a chemoresistance-driving subtype in OS, activating IGF-1R/Akt signaling to promote cancer stemness." (PMID 40909292, 2025). "Insulin resistance and hyperinsulinemia in diabetes further drive cancer progression by activating IR and IGF‐1R pathways, particularly the PI3K/AKT/mTOR cascade, which enhances cell proliferation, survival, and angiogenesis." (PMID 40387523, 2025). "Single-cell studies also identify COL11A1+ CAFs as a chemoresistance-driving subtype in OS, activating IGF-1R/Akt signaling to promote cancer stemness." (PMID 40909292, 2025). "Some studies report increased affinity of certain IGF1 isoforms to IGF1R, implicating them in cancer development." (PMID 39796756, 2025). "IGF1R promotes cancer cell proliferation and differentiation by inducing phosphorylation of PI3K and AKT." (PMID 40041495, 2025). "mCC-IR, cCC-IR, VIR, m-IGF1R and c-IGF1R were found to be heterogeneously expressed within the cancer tissue." (PMID 39775131, 2025). "A large percentage of cancer cells have an increased level of the Insulin‐like Growth Factor‐1 Receptor (IGF‐1R)." (PMID 39434498, 2025). "It has been shown that activation of the IGF1R–/PI3K/AKT pathway increases the expression of cancer stemness markers NANOG and SOX2." (PMID 40243906, 2025). "Cancer cells with strong cytoplasmic IGF1R immunostaining (c-IGF1R 2+) were observed in only 2 (1.4%) and cancer cells with a weak cytoplasmic immunostaining (c-IGF1R 1+) were seen in 13 (9.3%) cases." (PMID 39775131, 2025). "Building on this, the present study demonstrates the critical role of cMET and IGF-1R signaling in cancer serum-induced anchorage-independent growth (AIG)." (PMID 40804939, 2025). "EpCAM, HER2, CD44, and IGF1R were simultaneously detected and distinguished on four three different cancer cells lines (SK-BR-3, MDA-MB-231, and MCF-7)." (PMID 39997827, 2025). "The dysregulation of the PI3K/AKT/mTOR pathway in ASCC, driven by IGF2 from CAFs, highlights the potential of IGF2/IGF1R inhibitors as targeted treatments for this rare cancer." (PMID 40740483, 2025). "IGF-1R's upregulation in many cancer cells makes it a potential target for several cancer treatments, especially those involving small molecule inhibitors and monoclonal antibodies." (PMID 40071065, 2025). "This positive outcome in this thyroid condition underscores our insufficient knowledge of IGF-1R in cancer." (PMID 39638246, 2024). "Accordingly, vesicles from CAFs led to the activation of the IGF1R/PI3K/AKT pathway in cancer and endothelial cells, thereby accelerating lymph angiogenesis." (PMID 38892104, 2024). "For the PPTP/C models, higher INSR expression was associated with reduced activity of cixutumumab, consistent with results for adult cancer models showing that signaling through both IR-A and IR-B can mediate resistance to antibodies blocking IGF1R signaling." (PMID 39510293, 2024). "In particular, engagement with integrins, namely β1-(ITGB1) or β3-integrin (ITGB3), has been shown to enhance IGF-1R signaling in cancer cell models, fibroblasts, and endothelial cells." (PMID 39608716, 2024). "Here, we further investigated how adhesion signaling influences IGF-1R location and activity in migratory cancer cells and R- fibroblasts." (PMID 39608716, 2024). "Resistance to PI3K inhibition in cancer cells occurs via activation of different compensatory mechanisms or adaptive responses, including the activation of the IGF1R pathway." (PMID 38420122, 2024).
cancer (continued). "Previous studies have shown that the overexpression of IGF-1R is associated with poor chemotherapy outcomes, while the inhibition of IGF-1R leads to improved chemotherapy responses in different types of cancers." (PMID 38540176, 2024). "A variety of IGF-1/IGF-1R inhibitors have entered clinical development in the cancer field, including IGF-1-R tyrosine kinase inhibitors (including sorafenib) and mAbs against IGF-1-R and IGF-1." (PMID 39796700, 2024). "Following this, we focused our study on how ITGB1 expression affects IGF-1R activity in migratory cancer cells." (PMID 39608716, 2024). "The upregulation of uri1 and igf1r genes is commonly observed in various cancer types, serving as a characteristic feature." (PMID 38491378, 2024). "In summary, activation of IGF1R signaling is necessary for the acquisition of cancer cell plasticity, priming epithelial plastic cancer cells for the paracrine action of TME-derived factors at early/intermediate stages of cSCC progression." (PMID 39075581, 2024). "Targeting IGF1R through an antisense oligodeoxynucleotide (IMV-001) has proven to be an excellent strategy to increase the immunogenicity of cancer cells as demonstrated by the use of the IGV001 cancer vaccine." (PMID 38420122, 2024). "The findings demonstrate that integrin-mediated adhesion signaling can control and enhance IGF-1R activity through the CT Tyr1250/1251 phospho-site, thereby promoting a transformed and migratory phenotype in aggressive cancers." (PMID 39608716, 2024). "Linsitinib is one of the drugs developed as an IGF-1R tyrosine kinase inhibitor and has entered clinical trials for various cancers." (PMID 39693285, 2024). "Multiple anti-IGF1R MABs entered clinical evaluation, with many of the agents being studied against pediatric cancers." (PMID 39510293, 2024). "Insulin also binds to insulin-like growth factor-1 receptor due to highly similar structure and activates the downstream signaling pathway in prostate cells, thereby proliferating cancer cells." (PMID 39781138, 2024). "Previous studies have documented the involvement of the IGF-1/IGF-1R signaling pathway in regulating cancer stem cells across various tumors, sustaining stem cell-like properties, and fostering drug resistance." (PMID 38413558, 2024). "Pro-neoplastic activity was positively associated with the expression of phosphorylated-insulin-like growth factor-1 receptor (p-IGF1R) and negatively associated with the human epidermal growth factor receptor 2 (EGFR-2) in OESCC cancer tissues." (PMID 39120301, 2024). "IGF1R abrogation or inhibition in mixed cSCCs blocks epithelial plastic cancer cells in an epithelial state, reducing the generation of mesenchymal cancer cells." (PMID 39075581, 2024). "BMS-754807 suppresses PI3K/AKT/mTOR downstream of IR/IGF-1R, thus sensitizing cancer cells to CP and potentially increasing autophagic flux through suppression of mTOR." (PMID 38786030, 2024). "Encouraging pre-clinical observations with novel IGF-1R antagonists and epidemiological surveys linking IGF-1 levels to cancer risk, led to many clinical trials with biologicals and small molecules, but with sobering results." (PMID 39638246, 2024). "For example, the insulin-like growth factor receptor IGF-1R, which is overexpressed in cancer cells, binds to extracellular VIM." (PMID 39766058, 2024). "Further investigations on the Igf1r conditional KO mice aimed to elucidate the influential effects on cancer metastatic growth." (PMID 38255007, 2024). "IGF-1 stimulates most steps of cancer progression by signaling through the IGF-1 receptor (IGF-1R), and IGF-2 promotes tumor growth through binding primarily to the insulin receptor subtype A (IR-A)." (PMID 38396692, 2024).
cancer (continued). "To evaluate at which cancer cell state IGF1R signaling is relevant for cSCC progression, we also abrogated IGF1R expression in EpCAMlow cancer cells using 2 different sh-RNA constructs." (PMID 39075581, 2024). "PRKCSH’s diverse functions, including regulation of IGF1R and IRE1α, implicate it as a therapeutic target and biomarker in cancer immunotherapy." (PMID 38571496, 2024). "Although extensively deliberated, it remains unresolved why IGF-1R inhibition has been largely ineffective in cancer, yet was successful in an inflammatory context." (PMID 39608716, 2024). "Consistent with the results in PRKCSH-deficient cancer cells, overexpression of PRKCSH-WT or ΔG2B in H460 cells increased IGF1R protein levels." (PMID 38200153, 2024). "Activation of IGF-1R signaling promotes cancer cell proliferation and survival by stimulating cell cycle progression and inhibiting apoptosis." (PMID 39328205, 2024). "Here, after briefly summarizing the IGF1R signaling pathway in cancer, we review its role in regulating immune cells function and activity, and discuss IGF1R as a promising target to improve anti-cancer immunotherapy." (PMID 38420122, 2024). "TGFβ1 also induced ITGAV expression in sh-control plastic cancer cells, while this effect was significantly reduced in sh-IGF1R cancer cells." (PMID 39075581, 2024). "IGF1R-targeted inhibitors have also been under active development in recent years, but all of them have ended in failure due to their toxicity or inefficacy, so drugs targeting the IGF1R to treat cancer remain to be explored." (PMID 39404930, 2024). "To investigate the relationship between the expression levels of PRKCSH and IGF1R in cancer patient tissues, we first analyzed IGF1R mRNA expression in various cancer tissues using the TCGA database." (PMID 38200153, 2024). "A major one is the role of IGF-1R in three key aspects; aging, neurodegeneration, and cancer, as both detrimental and beneficial actions have been documented." (PMID 39638246, 2024). "A recent study focusing on various cancer cell lines indicated that phosphorylated IGF1R is transported to the nucleus where it acts as a transcriptional factor." (PMID 38182007, 2024). "At later stages, cancer cells can progress to the mesenchymal phenotype in response to stromal signals already independently of IGF1R signaling." (PMID 39075581, 2024). "The analysis of cancer cell features after cSCC growth showed that the generation of mesenchymal EpCAMneg cancer cells was significantly reduced in sh-IGF1R-derived tumors compared with the control group." (PMID 39075581, 2024). "IGF-1R signaling diminishes chemotherapeutic responses in BC through various mechanisms, including promoting proliferation, enhancing cancer stemness, and inhibiting apoptosis via DNA damage repair." (PMID 39273251, 2024). "The insulin-like growth factor 1 receptor (IGF1R) is a transmembrane tyrosine kinase receptor found abundantly in numerous cancers." (PMID 38674496, 2024). "To corroborate the involvement of IGF1R signaling in cancer cell plasticity acquisition, we pharmacologically inhibited IGF1R signaling in mixed cSCCs with OSI-906 inhibitor." (PMID 39075581, 2024). "Targeting HDAC1 to modulate IGF1R SUMOylation holds significant implications for cancer research and therapy." (PMID 39723246, 2024). "Genetically engineered retroviruses expressing IGF1R antisense RNA have been used to block IGF1R in cancer cells." (PMID 38892104, 2024). "In normoglycemic individuals, insulin secretion and IGF-1R activation are tightly regulated, resulting in a more controlled rate of cancer cell growth." (PMID 39290325, 2024). "We observed that IGF1R inhibition reduces ITGAV expression in cancer cells, accordingly with the EMP reduction of these cells." (PMID 39075581, 2024). "The activation of IGF-1R has anti-apoptotic effects on cancer cells, which contributes to cancer development and progression." (PMID 38540176, 2024).